NOS3 (nitric oxide synthase 3)
Diseases named in the same sentence as NOS3 in open-access papers (continued):
Sharing a sentence is not in itself a finding about the gene and the disease.
migraine (25 papers, 2010 to 2025). "Genotypic and allelic frequency distribution analysis of the NOS3 rs1799983 variant between migraine cases and control subjects." (PMID 36698892, 2022). "Genotypic and allelic frequency distribution analysis of the NOS3 rs1799983 variant in migraineurs according to the typical duration of migraine attacks (≤ 24 vs. >24 h)." (PMID 36698892, 2022). "Among the eight papers discussing NOS3 +894G>T, six reported genotype and allele frequencies for all participants and for overall migraine as well as those stratified by aura, while the remaining two did not." (PMID 26098763, 2015). "A number of recent observations concerning the association between TNF –308G>A and NOS3 +894G>T and migraine support a significant genetic component to predisposition toward this frequently undiagnosed disabling disorder, but the results are controversial." (PMID 26098763, 2015). "By considering high prevalence of migraine in society, the aim of this study was to determine the effect of NOS3 gene Glu298Asp polymorphism in the production of NO and investigating the response of this polymorphism to TCAs treatment in migraine attacks." (PMID 25422735, 2014). "Mean frequency of migraine attacks after use of TCAs was significantly decreased in all genotypes of NOS3 Glu298Asp polymorphism particularly in TT genotype (P < 0.05)." (PMID 25422735, 2014). "Although allelic and genotypic frequency distribution analysis did not support an association between migraine susceptibility and the examined variants in the overall population, subgroup analysis indicated significant correlation between NOS3 rs1799983 and migraine susceptibility in males." (PMID 36698892, 2022). "Hence, homozygosity for the NOS3 rs1799983 more common G allele seems to be associated with substantially increased migraine susceptibility in male population." (PMID 36698892, 2022). "Genetic susceptibility to migraine has been linked to the polymorphism in the NOS3 gene." (PMID 35627115, 2022). "However, haplotypes CCaGluG and “CCbGluG” of the NOS3 gene (p < 0.0015) were associated with migraines with auras." (PMID 32111088, 2020). "We performed a meta-analysis of case-control studies to evaluate whether the TNF –308G>A and NOS3 +894G>T polymorphisms confer genetic susceptibility to migraine." (PMID 26098763, 2015). "To clarify this association, we performed a meta-analysis of case-control studies to evaluate whether the TNF –308G>A and NOS3 +894G>T polymorphisms confer genetic susceptibility to migraine." (PMID 26098763, 2015). "Interestingly, there was a significant difference in the distribution of NOS3 allelic haplotypes (including T-786C) in patients with glaucoma and a history of migraine compared to controls suggesting some association with vascular dysfunction in glaucoma patients." (PMID 22919264, 2012). "PTGS2, PTGS1, PPARG, ADRB2, GABRA1, and NOS3 are potential targets for the treatment of migraines using ginkgo seeds due to their advantageous values." (PMID 41009787, 2025). "We also found associations between the expression of CALCA, EDN1, IL6, NOS3, VCAM1, and VEGF and measures of cerebrovascular function and migraine-related disability when menstrual phase (i.e., follicular, mid-cycle, or luteal) was accounted for." (PMID 38338971, 2024). "The GA genotype of NOS3 SNVrs743506 was more common in the control group than in patients with migraines with auras." (PMID 32111088, 2020). "Mean frequency of migraine attacks after use of TCAs based on paired sample t-test with P < 0.05 was significantly decreased in all genotypes of NOS3." (PMID 25422735, 2014). "This study observed that NOS3 rs743506 and NOS2 2087G/A interact significantly in patients with migraine compared to control (p < 0.05), and this combination impacts the susceptibility to migraine." (PMID 35627115, 2022).
migraine (continued). "However, the prognostic role of NOS1, NOS2, NOS3 genes in the development of the common AH + TTH phenotype has not been studied in comparison with the second most common phenotype (AH + migraine)." (PMID 33809023, 2021). "Subgroup analyses suggested that the T allele of NOS3 +894G>T variant increased the risk of migraine among non-Caucasians, which was driven by associations for MA." (PMID 26098763, 2015). "Subgroup analyses suggested that the “T” allele of the NOS3 +894G>T variant increases the risk of migraine among non-Caucasians (co-dominant model: pooled OR = 2.10; 95% CI 1.14 – 3.88)." (PMID 26098763, 2015). "A NOS3 polymorphism was significantly associated with glaucoma with migraine, but not with NTG or POAG in a case-control study." (PMID 20309402, 2010). "Moreover, with regard to NOS3 +894G>T, not all information was available, which would have been valuable to draw clear associations with migraine among populations of different ethnicities." (PMID 26098763, 2015). "Our findings appear to support the hypothesis that the TNF –308G>A polymorphism may act as a genetic susceptibility factor for migraine among non-Caucasians and that the NOS3 +894G>T polymorphism may modulate the risk of migraine among non-Caucasians." (PMID 26098763, 2015). "Thus, this study suggests that NOS3 haplotypes may influence the sensitivity to aura in migraine patients despite the lack of associations between NOS3 haplotypes and migraines." (PMID 35627115, 2022). "Interesting overlapping candidate genes for migraine and glucose-related traits are MTHFR, INSR, TNF, ESR1, NOS3, and PON1." (PMID 35627115, 2022). "Despite their plausible associations with migraine, this meta-analysis revealed no general associations between the TNF –308G>A or NOS3 +894G>T polymorphism and migraine risk." (PMID 26098763, 2015).
diabetic nephropathy (24 papers, 2010 to 2025). "The aim of this study was to assess the role of selected NOS polymorphisms—rs3782218 (NOS1), rs1137933 (NOS2), rs1799983, rs2070744, and rs61722009 (NOS3)—in the risk of developing diabetic nephropathy and in the likelihood of renal replacement therapy." (PMID 39061907, 2024). "Another study, which concerned the assessment of NOS3 polymorphisms in the context of the risk of developing diabetic nephropathy, concerned the analysis of rs1799983, rs2070744, and 27-bp VNTR polymorphisms." (PMID 39061907, 2024). "The variable number of tandem repeat (VNTR) polymorphisms in the NOS3 has been shown to be associated with the development of diabetic nephropathy." (PMID 39061907, 2024). "Another study focused on assessing NOS3 polymorphisms in the context of the risk of diabetic nephropathy concerned the analysis of polymorphisms: rs1799983, rs2070744 and 27-bp VNTR." (PMID 33374571, 2020). "The NOS3 −786 T>C and Glu298Asp polymorphisms were also linked with diabetic nephropathy." (PMID 35627115, 2022). "A study involving Japanese patients showed that the VNTR of the NOS3 might be associated with the progression of diabetic nephropathy in people diagnosed with T2D." (PMID 33374571, 2020). "What is more, lower NOS3 concentrations were observed in patients with diabetic nephropathy (p < 0.001) and in patients with diabetic nephropathy after kidney transplantation (p < 0.001) compared to the control group." (PMID 39061907, 2024). "The logistic regression was used to assess the risk of developing diabetic nephropathy or the likelihood of renal replacement therapy based on NOS1, NOS2, and NOS3 polymorphisms." (PMID 39061907, 2024). "It was similar in the case of genotype 4b/4b, where lower NOS3 concentrations in patients with diabetic nephropathy (p < 0.001) were also observed and in patients after kidney transplantation (p < 0.001) compared to the control group with the same genotype." (PMID 39061907, 2024). "However, it was noted that individual genotypes within the NOS3 polymorphisms (rs1799983, rs2070744, and rs61722009) were associated with differences in NOS3 concentrations between the diabetic nephropathy group and the kidney transplant diabetic nephropathy group and the control group." (PMID 39061907, 2024). "It was similar in the case of patients with the G/T genotype, where lower NOS3 concentrations were also observed in the diabetic nephropathy group (p < 0.001) and in the kidney transplant diabetic nephropathy group (p < 0.001) compared to the control group." (PMID 39061907, 2024). "The case-control study among diabetic patients with and without diabetic nephropathy showed a significant association with diabetic nephropathy in CNDP1, NOS3, and MnSOD genes." (PMID 37187702, 2023). "In T2D, polymorphisms in the NOS3 seem to attract particular attention, such as the tandem repeat polymorphism (VNTR) of the NOS3, which has been associated with the development of diabetic nephropathy." (PMID 33374571, 2020). "Significantly lower NOS3 concentrations were observed in patients with diabetic nephropathy and the 4a/4b genotype (p < 0.001) and in patients after kidney transplantation and with the 4a/4b genotype (p < 0.001) compared to the control group with the same genotype." (PMID 39061907, 2024). "The aim of this study was to assess the frequency of selected polymorphisms of genes encoding all three NOS isoforms—NOS1, NOS2, and NOS3—in patients with diabetic nephropathy, both after and without kidney transplantation." (PMID 39061907, 2024). "However, lower NOS3 concentrations were observed in the diabetic nephropathy group with the G/G genotype (p < 0.001) and in the kidney transplant diabetic nephropathy group with the G/G genotype (p = 0.001) compared to the control group with the same genotype." (PMID 39061907, 2024). "In this study we tested whether the protective effect of homoarginine is nitric oxide synthase‐3 (NOS3)‐independent in diabetic nephropathy (DN)." (PMID 33713581, 2021).
Nephropathy (23 papers, 2010 to 2025). A nonspecific term referring to disease or damage of the kidneys. "For the NOS3-rs1799983, however, the additive model has the least p value for the association of nephropathy and T2DM, compared to the other models in this variant." (PMID 30719346, 2019). "Two variants in NOS3 (rs3918226 and rs891511) were associated with kidney damage in the UKB cohort." (PMID 38858654, 2024). "The C-T haplotype of NOS3 was found to be significantly associated with both definitions of albuminuria in Mexican Americans, strongly implicating this gene in the susceptibility to kidney damage." (PMID 21054877, 2010). "Among the NEMG predictive of kidney damage along with serum phenotypes in our patients (NOS3, ACP2 and SLC39A13), some of them have previously been linked to kidney disease." (PMID 38858654, 2024). "Our results confirm previously identified associations of NEMG (NAT8, GATM, SLC22A2, WDR72, NOS3, AGXT2 and CPS1) with kidney disease and kidney function, providing new information that expands these associations to other kidney disease biomarkers." (PMID 38858654, 2024). "The objectives of the current study were to determine the frequency of NOS3 27-bp VNTR in ADPKD patients and to further investigate the modification of renal disease progression in ADPKD by the NOS3 27-bp VNTR genotypes." (PMID 25340172, 2014). "Variants in NOS3 and APOE, and the DMR on chromosome 14, appear to be associated with established kidney disease and may play a central role in the accelerated decline of kidney function in MeN." (PMID 40429630, 2025). "Since, in this study, DMF did not alter BP, plasma markers of kidney damage, or Nos3 gene expression and did not reduce NOS activities in the LHV under control conditions, LHV hypertrophy observed in DMF-treated rats must be attributed to other mechanisms." (PMID 39199192, 2024).
cardiac hypertrophy (21 papers, 2010 to 2025). "For instance, NOS1 and NOS3 deficiency lead to cardiac hypertrophy and each induces expression of different genes, although only NOS3-deficient mice are hypertensive." (PMID 25405382, 2015). "Nitric oxide and its downstream target, protein kinase G, are generally considered to blunt hypertrophy whereas nitric oxide synthase-3 uncoupling induces marked cardiac hypertrophy, dilation, and dysfunction." (PMID 23675503, 2013). "We hypothesized that altered NOS3 function and endogenous NO production may influence myocardial hypertrophy in athletes." (PMID 26517550, 2015). "Indeed Nos3 KO mice just like triple Nos1, Nos2, Nos3 KO mice develop cardiac hypertrophy." (PMID 35874523, 2022). "Therefore, Glu to Asp amino acid substitution at codon 298 in the NOS3 enzyme and reduced NO production may result in altered biological effects, including impaired vasodilation and increased myocardial hypertrophy." (PMID 26517550, 2015). "Herein, we show that NOS3 expression is not affected in early cardiac hypertrophy induced by angiotensin II and that PDE5A keeps a Z-band localization pattern." (PMID 21151982, 2010). "NOS1 and NOS2 may also slightly prevent cardiac hypertrophy since hypertrophy is significantly higher in triple KO mice in comparison to Nos3 KO mice, however, Nos1 or Nos2 KO mice do not develop cardiac hypertrophy." (PMID 35874523, 2022). "Early cardiac hypertrophy induced by angiotensin II did not change either NOS1 or NOS2 mRNA expressions (not illustrated), NOS3 mRNA expression or NOS3 protein expression." (PMID 21151982, 2010).
ischemic stroke (20 papers, 2007 to 2025). A stroke disorder caused by obstruction of blood flow to the brain, due to thrombotic (local blood clot formation) or embolic (due to a blood clot or other material traveling from another site) event. "One of these genes, the endothelial nitric oxide synthase gene (NOS3) has been reported as a genetic risk factor for ischemic stroke." (PMID 18070351, 2007). "Therefore, NOS3’s properties make it a biologically plausible candidate to investigate as a susceptibility gene in ischemic stroke for particular population groups." (PMID 38550935, 2023). "Additionally, the intron 4c allele in the NOS3 gene was linked with large artery ischemic stroke among African Americans in a small sample of 377 patients with ischemic stroke." (PMID 34828431, 2021). "The endothelial nitric oxide synthase gene, (NOS3), has been the focus of recent investigations as a potential genetic risk factor in the development of ischemic stroke." (PMID 18070351, 2007). "There has been one report studying the NOS3 gene in a biracial population of Caucasians and African-Americans with ischemic stroke." (PMID 18070351, 2007). "It was reported that in African American women, two SNPs in the NOS3 promoter but not the intron 4 or G894T alleles were associated with ischemic stroke." (PMID 18070351, 2007). "Given the absence of a significant main effect for either HBA CNV or the NOS3 SNP on incident ischemic stroke in this cohort, we did not pursue a model with both main effects nor did we test for interaction." (PMID 37622047, 2023). "Although some NOS3 variants have been described to increase the risk for certain conditions like pregnancy- induced hypertension or ischemic stroke, no clear monogenic disorder has been described for NOS1, NOS2, or NOS3." (PMID 38397443, 2024).
breast carcinoma (19 papers, 2011 to 2026). "A study on Taiwanese women found that the effect of NOS3 polymorphisms on breast cancer risk varies significantly according to the menopausal status." (PMID 41528397, 2026). "In breast cancer tumors, it was positively associated with ER and PR status; also, SNPs in NOS3 in breast cancer patients have shown associations with invasive cancer and poor prognosis." (PMID 39596349, 2024). "The results showed that the abnormal expression of 4 hub genes (PTGS2, ESR1, FOS, and NOS3) was associated with unfavorable overall survival of breast cancer patients." (PMID 33149754, 2020). "It was found to promote angiogenesis via PI3K/Akt/mTOR pathway, and enhance the migration and invasion via NOS3-NO-sGC-cGMP signaling in breast cancer cells." (PMID 33747912, 2021). "It has also been described a correlation between NOS3 expression and progression of malignancy in human breast cancer." (PMID 31354524, 2019). "In breast cancer, the increasing expression of NOS3 was reported to be a pro-angiogenic factor." (PMID 33747912, 2021). "Therefore, SRC and NOS3 play an important role in the progression of breast cancer." (PMID 36016606, 2022). "In accordance with our findings, previous studies have shown that NOS3 and AGTR1 are related to the chemoresistance of cancer: NOS3 is related to oxaliplatin resistance in colorectal cancer cells, and AGTR1 is a marker of the drug resistance of breast cancer." (PMID 35513851, 2022).
Cerebral ischemia (17 papers, 2009 to 2025). Restriction of arterial blood supply to the brain associated with insufficient oxygenation to support the metabolic requirements of the tissue. "In contrast, an increase in NOS3 expression in brain ischemia–reperfusion injury improved and released neuronal injury but inhibited tissue inflammation, oxidative stress, and apoptosis." (PMID 37064204, 2023).
myocardial ischemia (17 papers, 2014 to 2026). A disorder of cardiac function caused by insufficient blood flow to the muscle tissue of the heart. "Nitric oxide (NO) derived from endothelial NO synthase (NOS3) plays a central role in myocardial ischemia/reperfusion (I/R)-injury." (PMID 24346018, 2014). "In addition, the co-presence of the SNPs rs5215_G/G of KCNJ11 and rs1799983_T/T of the nitric oxide synthase 3 (NOS3) gene may play a protective role against myocardial ischemia." (PMID 37240691, 2023). "Prolonged myocardial ischemia decreased NOS activity and e-NOS (NOS-3) protein expression, but the new findings of our results show an increase in e-NOS expression in ischemic hearts pretreated with 50 mg dose of Sitagliptin." (PMID 30340421, 2018). "Network pharmacology analysis identified NOS3 and PTGS2 as core acute myocardial ischemia targets." (PMID 37234713, 2023).
Alzheimer disease (16 papers, 2009 to 2025). A progressive, neurodegenerative disease characterized by loss of function and death of nerve cells in several areas of the brain leading to loss of cognitive function such as memory and language. "A heterozygous mutation (c.1752 + 3G > A) was found in the Alzheimer’s disease (AD) susceptibility gene NOS3, and AD was suspected." (PMID 36298800, 2022). "The association between the G894T polymorphism (Glu298Asp) of nitric oxide synthase 3 (NOS3) and risk of Alzheimer’s disease (AD) was explored by performing a meta-analysis of case-control studies." (PMID 26337484, 2015). "NOS3 was reported to show various polymorphisms and a significant association with Alzheimer’s disease." (PMID 25356910, 2014). "Case–control studies genotyping the common structural polymorphism Glu/Asp at codon 298 of the NOS3 gene suggest that NOS3 may represent an important genetic risk factor for Alzheimer’s disease (AD)." (PMID 41465406, 2025). "Danazol and miconazole target ESR1 and NOS3, both associated with Alzheimer’s disease." (PMID 31481665, 2019).
chronic kidney disease (16 papers, 2014 to 2024). Impairment of the renal function secondary to chronic kidney damage persisting for three or more months. "Several studies have recently been conducted to investigate the role of NOS3 gene polymorphisms and end-stage renal disease (ESRD)." (PMID 35138322, 2022). "Higher frequency of the NOS3 4a allele carriers among CKD children suggests that the NOS3 VNTR may be associated with an increased risk of chronic renal failure." (PMID 25340172, 2014). "Other variants in NOS3 have shown a clear link with end-stage renal disease (ESRD), chronic kidney disease (CKD), CKD progression and diabetic kidney disease (DKD)." (PMID 39258111, 2024). "NOS3 influences plasma levels of nitric oxide metabolites and has been suggested to be involved in chronic renal failure." (PMID 35069435, 2021).